HIF1A (hypoxia inducible factor 1 subunit alpha)
Diseases named in the same sentence as HIF1A in open-access papers (continued):
Sharing a sentence is not in itself a finding about the gene and the disease.
tumor (continued). "We previously reported that STIM1 is upregulated during tumor growth and correlates with elevated hypoxia-inducible factor-1 alpha (HIF-1α) in hypoxic HCC." (PMID 32483465, 2020). "In this context, down-regulation of HIF-1α in tumor cells resulted in vessel normalization and maturation, and consequently less hypoxia." (PMID 33142239, 2020). "We also observed increased positive staining of both osteocalcin and HIF-1α, which permits hypoxic tumor cells to upregulate proteins that promote their survival and increase their aggressiveness, in tumors derived from MG-OKS cells." (PMID 33008481, 2020). "High-level expression of HIF-1α is positively correlated with tumor progression and poor prognosis in patients with GBM." (PMID 31530290, 2019). "Reports also suggest DAPK is a tumor suppressor and mediates degradation of cytoplasmic HIF-1α and a possible treatment strategy for Th17-assocciated inflammatory disease." (PMID 30414085, 2019). "High expression of PVT1 in tumor cells can be used as a competing endogenous RNA sponge to adsorb miR-199a-5p or miR-186 and subsequently upregulate the expression of HIF-1α." (PMID 31309249, 2019). "While in a nutrient-deficient hypoxic microenvironment, where hypoxia itself keeps the immune system in check, tumor cells in a HIF1α-dependent fashion can downregulate TDO2 expression so as to conserve Trp." (PMID 31866995, 2019). "It is becoming increasingly evident that hypoxia exerts significant effects on cellular metabolism via HIF-1α and is found to be the common link between hypoxia, metabolic adaptation, and tumor progression." (PMID 30754624, 2019). "Hypoxia-inducible factor-1α (HIF-1α) mediates tumor cell adaptation to hypoxic conditions and is a potentially important anticancer therapeutic target." (PMID 30755586, 2019). "RBMS3 was found to suppress tumor angiogenesis by regulating HIF1α expression, which implicated the strong correlation between RBMS3 and tumor metastasis." (PMID 30819235, 2019). "HIF-1α overexpression has several effects on tumor cell phenotypes: immortalization, stem cell maintenance, epithelial to mesenchymal transition, protumoral autocrine signaling, metabolic reprogramming, invasion, radioresistance and neoangiogenesis." (PMID 30708988, 2019). "The deletion of SIRT2 and SIRT3 stimulated HIF-1α expression and activity, thereby promoting Glut1 expression, glucose uptake and tumor growth." (PMID 31849939, 2019). "HIF-1α acts as a tumor suppressor, while HIF-2α acts as an oncogene on ccRCC development and progression." (PMID 31311512, 2019). "Thereby, it is supposed to mediate a switch from HIF-1α to HIF-2α-dependent transcription during tumor hypoxia by selectively degrading HIF-1α and promoting HIF-2α transactivation without affecting HIF-2α levels." (PMID 31208103, 2019). "Hypoxia (H) in stem cells and the tumour microenvironment promote CD133 expansion via upregulation of hypoxia-inducible factor 1-alpha (HIF-1α)." (PMID 30836718, 2019). "Pvt1 regulates the immunosuppression activity of granulocytic myeloid-derived suppressor cells (G-MDSCs), which is a subgroup of MDSCs, and Pvt1 is up-regulated by HIF-1α under hypoxia conditions in tumor-bearing mice." (PMID 31850189, 2019). "Although a small amount of pathological tissue can be obtained by biopsy, the expression of HIF-1α cannot accurately reflect the hypoxic state of the tumour due to the heterogeneity of the tumour." (PMID 31886169, 2019). "To assess the effect of HIF-1α on PTBP3-mediated tumor growth in vivo, we used 2-MeOE2 to block HIF-1α pathway in the xenografts formed by HCT116 PTBP3 Con/OE cells." (PMID 31291975, 2019). "Taken together our findings suggest a role for HIF-1α in the development of antiestrogen treatment-resistance and progression into a more aggressive tumor phenotype." (PMID 31821370, 2019).
tumor (continued). "In the adjacent nontumor tissues, HIF-1α primarily localized to the cytoplasm, whereas in a considerable percentage of the tumor tissues, HIF-1α showed nuclear localization." (PMID 30177838, 2019). "Remarkably, the expression of HIF-1α was also down-regulated in miR-199a mimics transfected cells derived tumours compared with control miRNAs transfection in xenograft tumours." (PMID 28442599, 2019). "Elevated tumor growth has been observed in studies that use the active form of HIF-1α expressed by human skin fibroblasts co-injected with MDA-MB-231 cells." (PMID 30761299, 2019). "Tumor oxygenation influences HIF-1α expression to regulate the balance between pro- and anti-angiogenesis in neovasculature progression." (PMID 31695774, 2019). "Surprisingly, high quantities of NO produced by macrophages in response to HIF-1α can actually lead to tumor suppression and death in early stages." (PMID 30931508, 2019). "HIF-1α has a broad impact on tumors, including enhanced utilization of glucose, tumor cell stemness, migration, metastasis and so on." (PMID 30940798, 2019). "The role of chemokines in tumor angiogenesis was achieved in a CCR7-dependent manner through inhibiting Met/ERK/Elk-1/HIF-1α/VEGF-A pathway in CRC." (PMID 31214045, 2019). "In neoplasms, inordinate NF-κB promote the expression of many vital modulators of cancer progression, such as HIF-1α, AP-1, STAT3, and MUC1." (PMID 31781219, 2019). "Next, tumor tissue hypoxia and elevated HIF-1α expression stimulates reactive astrocytes to secrete the pro-angiogenic factor VEGF." (PMID 30732625, 2019). "In our study, the combination therapy of overexpressing miRNA-138 and inhibition of HIF1α in vivo showed eradicated tumor growth and metastasis." (PMID 31371307, 2019). "The high binding energies between AATP and HIF-1α contribute to suppression of activity of HIF-1α, resulting in downregulation of downstream reactions that relate to tumor metastasis and VM formation." (PMID 31022939, 2019). "We also showed that blocking HIF-1α pathway using HIF-1α inhibitor 2-Methoxyestradiol (2-MeOE2) significantly reduced tumor growth formed by PTBP3 overexpression (OE) cell." (PMID 31291975, 2019). "Although the expression of HIF-1α is relatively low in normoxia compared with that in hypoxia, it is still highly expressed in some malignant tumour cell lines." (PMID 31239858, 2019). "In contrast to the hypoxic situation, the availability of glutamine is responsible for the stabilization of HIF1α under normoxia in different tumor cell lines." (PMID 31554283, 2019). "The adaptation of tumor cells to hypoxia is possible with the help of transcription factor HIF-1α, which regulates several genes involved in tumor growth, including GLUT1." (PMID 31247901, 2019). "In order to understand the role of LOX-1 in promoting tumor growth and angiogenesis, we examined the expression of β-catenin and HIF-1α in the same tissues." (PMID 31608230, 2019). "Solid tumors possess unique microenvironments that include hypoxic conditions, also referred to as tumor hypoxia, and HIF-1α is an important transcription factor that regulates the cellular response to hypoxia." (PMID 30177838, 2019). "In this study, we showed that the tumor promoter TPA increased the HIF-1α transcriptional activity in a PKC-δ-dependent manner, and VK2 suppressed the TPA-stimulated HIF-1α transcriptional activity in a human HCC cell line." (PMID 30813635, 2019). "In some cases, Hif-1α, along with other hypoxia-related pathways such as unfolded protein response, also drive tumor cell autophagy." (PMID 31450598, 2019). "In recent years, YC-1 has emerged as potential hypoxia-targeted agent because of its inhibitory effect on HIF-1α, which is crucial for tumor angiogenesis under hypoxic microenvironment." (PMID 30634531, 2019).
tumor (continued). "This mutation augments functioning of the HBX protein and in turn upregulates the expression and transcriptional activity of hypoxia-inducible factor 1-alpha (HIF-1α) contributing to tumor development and progression." (PMID 31601912, 2019). "Hypoxia, via HIF-1α, directly up-regulates the expression of PD-L1 in various tumor cells (melanoma, lung, breast and prostate cancer) by directly binding the HRE in the promoter of PD-L1 gene." (PMID 31540045, 2019). "GRPR and other protein expressions distinctly increased with BN4 peptide treatment compared to BN3 and BNS; more metastasis and tumor growth was promoted via HIF-1α which increased angiogenesis." (PMID 30887136, 2019). "Evidence shows that tumor-derived EVs carrying hypoxia-inducible factor 1-alpha (HIF1α) and latent membrane protein 1 (LMP1) are significantly more often associated with increased cancer migration and enhanced invasiveness." (PMID 31795140, 2019). "Specifically, while HIF-1α is upregulated in tumor tissue compared to normal adjacent one, the expression of HIF-2α is downregulated." (PMID 31817513, 2019). "In vivo in SCC4 and SAS tumour-bearing mice, the combination of HIF-1α siRNA and PDT led to a significant decrease of tumour volume (40 %) after 10 days." (PMID 31671658, 2019). "HIF-1α expression was significantly correlated with age, tumor diameter, histological grade, lymph node status, and tumor TNM stage; c-myc expression was significantly associated with tumor diameter, histological grade, lymph node status, and tumor TNM stage." (PMID 31577739, 2019). "HIF-1α regulates the transcription of multiple genes in tumor cells after binding to its cognate enhancer sequence in the promoters of its target genes." (PMID 30038060, 2019). "HIF-1α also critically supports survival and self-renewal in cancer stem cells and disseminated tumor cells in metastasis sites." (PMID 30089913, 2019). "Immunohistochemical staining showed that HIF-1α expression in the tumor was significantly suppressed by melittin." (PMID 31057657, 2019). "In this particular context, HIF1α acts as a tumor suppressor gene, while HIF2α favors tumor development." (PMID 31861590, 2019). "The enhanced tumor oxygenation after oxygen microbubble treatment inhibited hypoxia inducible factor-1 alpha (HIF-1α)/vascular endothelial growth factor (VEGF) pathway to improve the morphology and function of tumor vasculature." (PMID 31695774, 2019). "It was noticeable that the mRNA of Hif1a in the tumor tissue of e-As4S4 group was also decreased significantly, which indicated that the level of HIF-1α protein was at least partly regulated by e-As4S4 transcriptionally." (PMID 31106156, 2019). "In conclusion, our study reveals an important post-transcriptional control mechanism of the tumor progression master regulator HIF-1α." (PMID 31291975, 2019). "Elevated levels of HIF-1α have been observed in tumor biopsies, and there was a strong correlation between HIF-1α levels, tumor angiogenesis, metastasis, and anticancer drug resistance." (PMID 31728210, 2019). "Given the essential role of HIF-1α in glucose metabolism, glycolysis is inhibited by the tumor suppressor, HOXA9." (PMID 31013831, 2019). "Several studies have reported that traditional Chinese medicine can inhibit tumour cells growth and angiogenesis by suppressing the expression of HIF-1α in normoxia." (PMID 31239858, 2019). "IHC results obtained in PT9 and PT10 PDX models showed that tumor growth and the expression of HIF1A, VEGFA1 and Ki-67 were efficiently suppressed by treatment with PX-478, alone or in combination with neratinib." (PMID 31018595, 2019). "In this line, it has been shown that bortezomib inhibits tumor adaptation to hypoxia by repressing HIF-1α expression and sensitizes cancer cells in hypoxia, supporting the combination of TFP and proteasome inhibitors for treating hypoxic tumors such as PDAC." (PMID 31769431, 2019).
tumor (continued). "With different clinical and experimental research establishing HIF as a cancer therapy target, HIF-1α and HIF-2α levels are associated with metastasis, vascularization, and tumor growth in both animal-based and clinical-based studies." (PMID 31485300, 2019). "Its effects on immune effectors are many: hypoxia has been recognized as an upregulator of the expression of PD-1/PD-L1 on tumor cells via HIF-1α, and impairing hypoxia sensitizes cancer cells to T cell checkpoint blockade with CTLA-4 and PD-1." (PMID 31396523, 2019). "In renal cell carcinoma (Rcc) HOTAIR is able to promote tumor progression through inhibition of miR-217 expression, and modulating the expression of HIF-1α and AXL receptor tyrosine kinase." (PMID 31072041, 2019). "Since HIF-1α plays an important role in tumor development under hypoxic conditions by controlling angiogenesis, cell survival and metastasis, it is an attractive target for anti-cancer therapy." (PMID 31061665, 2019). "Tumor-infiltrating MDSCs are more immunosuppressive than splenic MDSCs, primarily due to an increase in Arg1 activity and nitric oxide production via HIF-1α in these cells." (PMID 30925926, 2019). "Expression levels of PKM2, SHMT2, and HIF-1α, together with interleukin 6, were also analyzed utilizing normal and tumor FFPE tissues." (PMID 31500219, 2019). "Tumor grafts were removed and weighed at different time points and HIF1α-expressing cells were visualized using confocal laser scanning microscopy with an anti-HIF1α antibody." (PMID 33568892, 2019). "Long-term administration of angiogenesis inhibitors induces hypoxia in the tumor microenvironment by over-pruning blood vessels and up-regulates HIF-1α." (PMID 30845711, 2019). "The subcellular distributions of CXCR4 and HIF-1α in the primary tumor tissues served as predictors of metastasis in RCC, while they were not related to the presence of metastases." (PMID 30177838, 2019). "Recently, it has been demonstrated that ASA also decreases the expression of the hypoxia-inducible factor 1alpha (HIF1α), a key regulator of genes that are involved in metabolism under hypoxic conditions and a major determinant of tumor cell stabilization." (PMID 31878351, 2019). "Hypoxia-inducible factor 1α (HIF-1α) is a master regulator of adaptive responses to hypoxia and promotes critical steps in tumor progression as well as obesity." (PMID 31141984, 2019). "During CRC development, factor inhibiting HIF-1α (FIH-1) represses the HIF-1α pathway, suggesting that the association between FIH and HIF affects tumor development." (PMID 31817259, 2019). "In the advanced tumor stage, 84% and 57% of patients, while in lower stage group 30% and 46% of patients, were having elevated expression of HIF-1α, MDR1 and LAPTM4B." (PMID 30746305, 2019). "In vivo (650 nm, 500 mW∙cm−2, 15 min), the tumour in the BB NCs/laser group was totally destroyed and a low level of HIF-1α was detected." (PMID 31671658, 2019). "Hypoxia enhances ROS production; reciprocally, ROS assist tumor cells to adapt to hypoxia via stabilization of HIF-1α." (PMID 30669417, 2019). "In order to compensate for adequate oxygen delivery, increased expression of hypoxia inducible factor-1 alpha (HIF-1α) activates tumor cells to secrete vascular endothelial growth factor (VEGF) for angiogenesis." (PMID 31695774, 2019). "The dramatic increase of PDT effect was also proven In vivo in U14 tumour-bearing mice with an important decrease of tumour volume in comparison with irradiation of MB alone or SiO2-MB and a decrease of HIF-1α showing an improvement of hypoxia." (PMID 31671658, 2019). "HOXA9 can function as a tumor suppressor gene though downregulation of the HIF-1α gene in cutaneous squamous cell carcinoma (cSCC)." (PMID 31013831, 2019). "Results obtained from the western blotting analysis showed that the total HIF-1α expression of tumor lysate for the e-As4S4 group was much lower than that for r-As4S4 group, which was consistent with the IHC images." (PMID 31106156, 2019).
tumor (continued). "The activity of HIF-1α plays a central role in maintaining energy metabolism, tumor angiogenesis, and promoting tumor cell proliferation and metastasis." (PMID 31745161, 2019). "As an alternative, we propose that HIF-1α blockade should be used concurrently with the inhibition of HIF-2α in order to radiosensitize tumor cells, partly by reducing their basal-glycolytic activity." (PMID 30642030, 2019). "When tumor tissues grow, they will almost certainly be in hypoxic conditions, which subsequently results in increased HIF-1α expression." (PMID 33817155, 2019). "For example, angiogenesis is an important aspect of cancer progression, and HIF1A contributes to tumor angiogenesis by upregulating vascular endothelial growth factor (VEGF) and other proangiogenic factors." (PMID 31744467, 2019). "The expression level of HIF-1α was signally higher in the untreated tumor tissues, whereas its expression was markedly decreased after PMS treating." (PMID 31735093, 2019). "Mounting evidence provided that featuring a high tumor grade, HIF-1α is over-stated in numbers of human cancers, indicating that HIF-1α functions as an independent element of cancer prognosis." (PMID 31762805, 2019). "On the other hand, tumor with low HIF-1α and proangiogenic factors expression are more sensitive to microvascular damage after radiation." (PMID 31350968, 2019). "A wealth of evidence proves that high expression levels of HIF-1α in solid tumors and during tumor growth is significantly limited after knocking it out, which indicates that it exerts a vital role in cancer development." (PMID 31554859, 2019). "The in vivo studies further demonstrated that over-express of miR-199a exhibited reduced tumor growth with down-regulated K-RAS/AKT/ERK/HIF-1α signalings." (PMID 31681604, 2019). "Doxorubicin can upregulate HIF-1α levels in aerobic tumor cells by stimulating inducible nitric oxide synthase (iNOS) activity." (PMID 31788448, 2019). "An increase in intracellular oxygen leads to the degradation of the HIF-1α protein, which in turn, reduces tumor resistance against the drug." (PMID 31569523, 2019). "The analysis of pathways regulated by HIF1A exclusively in normoxic NB cells shows a role of HIF1A in metabolic process necessary for tumor cells viability." (PMID 30808328, 2019). "Hypoxia has many effects on tumor phenotypes, mostly driven by the selection of hypoxia-dependent genes such as HIF-1α." (PMID 30708988, 2019). "With cells under reduced oxygen tension, HIF-1α is translocated to the nucleus, where it activates transcriptional factors that in turn regulate tumor angiogenesis, migration, invasion, and metastasis." (PMID 31077234, 2019). "Lactate promotes the stabilization of HIF-1α and activates NF-κB and PI-3 kinase signalling in endothelial cells and induces the secretion of the proangiogenic factor VEGF from tumour-associated stromal cells." (PMID 31341492, 2019). "From this study, we conclude that HIF1a is strongly related to tumour genetics in UM, especially to loss of BAP1 expression, and less to tumour size." (PMID 31323773, 2019). "We also determined the protein levels of K-RAS, p-AKT, p-ERK1/2 and HIF-1α in tumor tissues, and found that these proteins from U87/miR-199a group were significantly lower than that of U87/miR-NC group, which is consistent with in vitro data." (PMID 31681604, 2019). "On the other hand, VM studies based on immunohistochemistry of tumor sections cannot deliver mechanisms, only association for example enrichment of EMT-related proteins or HIF-1α expression." (PMID 31428573, 2019). "The regulation of HIF1α activity is mechanistically linked to microtubules, and disruption of the microtubule cytoskeleton downregulates the HIF1-α pathway and tumor angiogenesis." (PMID 31877978, 2019). "Strong correlation between elevated levels of HIF-1α and tumor metastasis, angiogenesis and poor patient prognosis, as well as tumor resistance therapy, has been proven." (PMID 31291975, 2019).